XPO1 (exportin 1)
Diseases named in the same sentence as XPO1 in open-access papers (continued):
Sharing a sentence is not in itself a finding about the gene and the disease.
pancreatic cancer (22 papers, 2014 to 2025). "We found that XPO1 showed high expression in pan‐cancer and was associated with poor prognosis in hepatobiliary and pancreatic tumors." (PMID 36200270, 2023). "In conclusion, we analyzed data from TCGA and found that XPO1 showed high expression across cancers and was associated with poor prognosis in hepatobiliary and pancreatic tumors." (PMID 36200270, 2023). "We found that XPO1 was highly expressed across a range of cancers and associated with poor prognosis in hepatobiliary and pancreatic tumors." (PMID 36200270, 2023). "Previously, we have found that XPO1 inhibitors can restore the function of multiple tumor suppressive proteins including FOXO3a, p27, Par4 and p73, causing pancreatic cancer cell death in vitro and tumor inhibition in vivo." (PMID 31382411, 2019). "Increased XPO1 expression was shown in pancreatic cancer, and high expression was associated with increased serum levels of CEA and CA19-9, with tumor size, lymphadenopathy, and liver metastasis, and with shorter progression-free survival (PFS) and OS in uni- and multivariate analyses." (PMID 31052304, 2019). "Therefore, the methylation of the miR-30 gene could be one of the causes leading to the high expression of XPO1 in pancreatic cancer." (PMID 31382411, 2019). "Mutations and dysregulation of classical exportins such as CRM1 (also known as exportin 1) are frequent in B‐cell malignancies, gliomas, cervical, and pancreatic cancers." (PMID 40761481, 2025). "In this study, we report that the upregulation of XPO1 expression in pancreatic cancer is, in part, due to the hypermethylation of the miR-30 family gene in cancer cells, leading to the downregulation of the miR-30 family and the upregulation of XPO1." (PMID 31382411, 2019). "We also observed that the enforced expression of the miR-30 family inhibited the expression of XPO1, resulting in the suppression of pancreatic cancer growth both in vitro and in vivo." (PMID 31382411, 2019). "We have found that the inhibition of XPO1 significantly suppressed the pancreatic cancer cell growth in vitro and in vivo through retaining tumor suppressors in the nucleus." (PMID 31382411, 2019). "Because we found that XPO1 is a direct target of the miR-30 family, we transfected the miR-30 mimic into pancreatic cancer cells." (PMID 31382411, 2019). "By measuring the growth index, we found that miR-30a and miR-30b mimic inhibited the growth of MiaPaCa-2 and Panc-1 pancreatic cancer cells which have a high expression of XPO1 compared to normal pancreatic HPDE and HPNE cells." (PMID 31382411, 2019). "The high expression of XPO1 in cancer cells is correlated with the aggressive progression and poor prognosis of cancers including pancreatic cancer." (PMID 31382411, 2019). "The upregulation of the miR-30 family can suppress pancreatic cancer cell proliferation and tumor growth in vitro and in vivo through the inhibition of XPO1 expression." (PMID 31382411, 2019). "One of the important signal transduction proteins involved in the regulation of pancreatic cancer’s aggressive progression is the nuclear export protein (XPO1)." (PMID 31382411, 2019). "Since we found the decreased expression of the miR-30 family in human pancreatic cancer tissues compared with normal pancreatic tissues, we expect that pancreatic cells should overexpress XPO1 if this protein is a direct target of the miR-30 family." (PMID 31382411, 2019). "In conclusion, we demonstrate that there is a regulatory axis (DNA methylation of miR-30 gene/miR-30/XPO1 mRNA and protein) in pancreatic cancer cells." (PMID 31382411, 2019). "This review focusses on the impact of XPO1 over-expression in pancreatic cancer therapy resistance and how this can be harnessed for the development of effective therapeutics to tame this deadly disease." (PMID 29735942, 2018). "XPO1 inhibition can inhibit several critical pathways that promote pancreatic cancer progression and therapy resistance." (PMID 29735942, 2018).
pancreatic cancer (continued). "Here we discuss several XPO1 inhibitors that have shown to exert potent anti-tumor activity in pre-clinical pancreatic cancer models as well as in cancer patients in clinic." (PMID 29735942, 2018). "Collectively, work from several laboratories clearly indicates that XPO1 is aberrantly over-expressed in pancreatic cancer." (PMID 29735942, 2018). "Leptomycin B and its analog, selinexor, are inhibitors of exportin-1 (XPO1) that have been tested for their efficacy in treating pancreatic cancer." (PMID 31867128, 2018). "This review highlights the current knowledge on the role of XPO1 in pancreatic cancer and how this serves as a unique and clinically viable target in this devastating and by far incurable cancer." (PMID 29735942, 2018). "In 2009 Huang and colleagues used 69 tumors and 10 normal tissues to demonstrate increased expression of XPO1 in pancreatic cancer." (PMID 29735942, 2018). "We have demonstrated that inhibition of XPO1 by the selinexor increases miR-145 expression in pancreatic cancer cells resulting in the decreased cell proliferation migratory capacities." (PMID 29735942, 2018). "RNAi of XPO1 blocked pancreatic cancer cell line growth and also inhibited pancreatic cancer stem cell-derived spheroid formation indicating to their role in this devastating disease." (PMID 29735942, 2018). "XPO1, often over-expressed in pancreatic cancer, mislocalizes the wild type tumor suppressors to the wrong cellular compartment, leading to their functional inactivation." (PMID 29735942, 2018). "Our analysis of pancreatic cancer cell lines, pancreatic cancer stem cells (derived from pancreatic cancer cell lines) showed enhancement in XPO1 expression." (PMID 29735942, 2018). "In view of the role of aberrant XPO1 expression in pancreatic cancer subsistence, the anti-tumor activity of SINE were studied in several pre-clinical and Phase Ib clinical trial." (PMID 29735942, 2018). "In patients suffering from Stage I and II pancreatic cancer, increased XPO1 protein expression was detected in malignant tissues." (PMID 25476752, 2014). "For example, higher levels of XPO1 expression are positively correlated with grade progression as well as increased proliferation rates in glioma, pancreatic cancer, and cervical cancer." (PMID 25461627, 2014). "Considered together, these results provide direct evidence of XPO1 nuclear export of p27 in pancreatic cancer." (PMID 25476752, 2014). "Serum CEA and CA19.9 levels, two well-known prognostic markers in pancreatic cancer, correlated with increased XPO1 protein expression in human tissues." (PMID 25476752, 2014). "In addition, increased XPO1 is known to correlate with elevated prognostic markers in pancreatic cancer, such as serum CEA and CA19.9, so it is theoretically possible to use it in predicting poor PFS and OS." (PMID 39459201, 2024). "Notably, in TCGA unpaired samples, XPO1 was highly expressed in hepatobiliary and pancreatic tumors (CHOL, LIHC, and PAAD)." (PMID 36200270, 2023). "Nuclear export Inhibitors based on study of XPO1 are used to therapy pancreatic cancer." (PMID 35711911, 2022). "Furthermore, XPO1 inhibition by selinexor increased miR-145 expression in pancreatic cancer cells, resulting in decreased cell proliferation and migratory capacities." (PMID 31052304, 2019). "In this study, we found that the high expression of XPO1 in pancreatic cancer cells could be, in part, due to the methylation of the miR-30 gene, leading to the low expression level of the miR-30 family." (PMID 31382411, 2019). "In addition, we also found that the XPO1 expression was higher in pancreatic cancer tissues compared with normal tissues whereas the miR-30 level was low in cancer tissues." (PMID 31382411, 2019). "The prognostic value of XPO1 in pancreatic cancer has already been established." (PMID 29735942, 2018).
pancreatic cancer (continued). "Despite the consistent observation showing enhancement in XPO1 expression in pancreatic cancer, the underlying mechanism for such activation is not clear." (PMID 29735942, 2018). "However, there is a paucity of data regarding the prevalence of XPO1 expression in clinical samples of pancreatic cancer, with only three studies, only including one that analyzed correlations with clinicopathological features and survival in a cohort of 76 patients." (PMID 31052304, 2019). "Therefore, the high expression of XPO1 found in pancreatic cancer and other tumors could be, in part, due to the low expression of the miR-30 family, which is caused by the hypermethylation of the miR-30 gene." (PMID 31382411, 2019). "However, the involvement of the exportins in pancreatic cancer remains unknown, except for XPO1." (PMID 33854580, 2021). "A significant decrease in viability was observed in simultaneous XPO1 + HSPA9 or RUVBL1/2 targeting in comparison with normal fibroblasts and typical chemotherapy protocols used for colon, lung or pancreatic cancers." (PMID 39217152, 2024). "High expression of the nuclear exporter chromosome maintenance region 1 (CRM1) or exportin 1 (XPO1), a common feature of several cancers including pancreatic cancer, results in excessive export of critical TSPs to the incorrect cellular compartment, leading to their functional inactivation." (PMID 29735942, 2018). "Therefore, it may be possible to use high XPO1 expression as a clinical parameter for predicting poor PFS and OS in pancreatic cancer." (PMID 25476752, 2014). "In the paired samples, we found that XPO1 was highly expressed in CHOL and LIHC compared with the corresponding normal tissues (pancreatic cancer pairing data lacked significance with only four pairs)." (PMID 36200270, 2023).
cervical carcinoma (21 papers, 2011 to 2025). A carcinoma arising from either the exocervical squamous epithelium or the endocervical glandular epithelium. "Another important issue we found here is the novel role of high-risk HPV E6 in cervical cancer progression through the exportin-1-mediated nuclear export of HP1γ." (PMID 32203172, 2020). "Herein, we suggest for the first time that exportin-1 inhibitor can be used in combination with cisplatin to ameliorate cervical cancer progression." (PMID 32825184, 2020). "Further clinical or pre-clinical studies are required to apply this approach for inhibiting exportin-1 in cervical cancer in combination with cisplatin." (PMID 32825184, 2020). "Inhibition of CRM1/Exportin 1-dependent nuclear export by treatment with LMB led to the nuclear import of EPS8 in cervical cancer cells." (PMID 30941306, 2019). "This suggests that Rad21 involves the development of cervical cancer possibly by participating in the regulation of cell cycle and the nuclear output of the tumor suppressor gene via XPO1." (PMID 29797792, 2018). "A comprehensive understanding of the molecular interactive mechanism between Rad21 and XPO1 in nuclear transport will lead to better miRNA therapeutic strategies for cervical cancer." (PMID 29797792, 2018). "The Rad21 gene involves the development of cervical cancer possibly by participating in the regulation of cell cycle and the nuclear output of the tumor suppressor gene by XPO1." (PMID 29797792, 2018). "In cervical cancer cell lines, silencing of the XPO1 protein by RNA interference resulted in increased cell death." (PMID 25476752, 2014). "In ovarian and cervical cancer, increased XPO1 nuclear and cytoplasmic protein expression was observed in malignant tissues when compared to benign lesions." (PMID 25476752, 2014). "In addition to these prior studies, we showed the aberrant nuclear export of HP1γ by exportin-1 in cervical cancer cells and tissues." (PMID 32825184, 2020). "Therefore, exportin-1 is very critical for cancer cell survival and high expression of exportin-1 has been reported in cervical cancer." (PMID 32203172, 2020). "Moreover, the analysis of GEO profiles (GDS3233) showed a significant increase in the expression of XPO1 in cervical cancer cell lines and cervical cancer tissues, compared with normal cervix epithelium tissues." (PMID 32203172, 2020). "Indeed, XPO1 levels are often elevated in tumors when compared with non-malignant cells of the same lineage, including pancreatic cancer, glioma, and cervical cancer." (PMID 25057921, 2014). "Interestingly, we found abnormal cytoplasmic localization of HP1γ, which results from increased binding with exportin-1, in HPV-infected cervical cancer cells and tissues." (PMID 32203172, 2020). "To address whether EPS8 is regulated by nucleus export, we treated both HeLa and C33A cervical cancer cells with Leptomycin B (LMB), a specific inhibitor of CRM1/Exportin 1-dependent nuclear export." (PMID 30941306, 2019).
prostate carcinoma (21 papers, 2013 to 2025). A carcinoma that arises from epithelial cells of the prostate gland. "Earlier we showed that increased XPO1 in prostate cancer is associated with a high Gleason score and bone metastasis." (PMID 34206543, 2021). "Moreover, increased XPO1 in prostate cancer has been found to be associated with increased Gleason score and bone metastasis." (PMID 30450161, 2018). "Increased XPO1 in prostate cancer is associated with a high Gleason score and bone metastasis." (PMID 30450161, 2018). "Increased XPO-1 expression, mainly in the nuclear compartment, was associated with increased Gleason score and bone metastatic potential supporting the use of SINEs in advanced prostate cancer." (PMID 26620414, 2015). "Therefore, we investigated the in vitro and in vivo effects of SINE on the regulation of AR and ARv in prostate cancer and the molecular mechanisms underlying XPO1 regulated AR and ARv in order to design a novel therapeutic strategy for the treatment of prostate cancer and CRPC." (PMID 30450161, 2018). "Coimmunoprecipitation (co-IP) assays confirmed that endogenous XPO1 interacted with TIRR in PC-3 prostate cancer cells." (PMID 39632881, 2024). "XPO1 inhibition by selinexor was also shown to sensitize prostate cancer cells to docetaxel through a mechanism involving the enhancement of DNA damage." (PMID 34206543, 2021). "High expression of cytoplasmic XPO1 shows correlation with prostate cancer and has added clinical value in tissue samples." (PMID 31018022, 2019). "XPO1 is overexpressed in various cancers including prostate cancer and is correlated with poor prognosis." (PMID 30450161, 2018). "By utilizing and analyzing the mRNA microarray data in Oncomine database, we observed more than eight sets of data which showed higher expression of XPO1 mRNA in prostate cancer tissues compared to normal prostate gland tissue." (PMID 30450161, 2018). "Our results suggest that survivin is an essential component of the downstream signaling pathway of XPO-1 inhibition in prostate cancer cells, intriguingly an increase in the total concentration of survivin can interfere with these drugs' antitumor effects." (PMID 26620414, 2015). "XPO-1 protein levels were high in prostate cancer when compared to non neoplastic prostate epithelial cells." (PMID 26620414, 2015). "Next, we analyzed and quantified the expression of XPO-1 in prostate cancer, normal or neoplastic prostate epithelial cells by immunoblots and by adjusted densitometry units." (PMID 26620414, 2015). "To determine the effects of XPO-1 inhibition on prostate cancer growth in vivo, we used two aggressive CRPC, PC3, DU145 and 22rv1, cell lines engrafted in male nude mice." (PMID 26620414, 2015). "Similarly, uc.63 can increase G2/M cells, inhibit cellular apoptosis, and promote BC and prostate cancer (PC) independently of the exportin-1 gene (Xpo1)." (PMID 37036543, 2023). "XPO-1 is overexpressed in prostate cancer compared to normal or hyperplastic tissues." (PMID 26620414, 2015). "We evaluated the expression of XPO-1 in human prostate cancer tissues and cell lines." (PMID 26620414, 2015). "Mechanistically, it was demonstrated that XPO1 mediated induction of SOX2, a key factor required for NE transformation in prostate cancer." (PMID 39858043, 2025). "These analyses identified multiple actionable targets, such as XPO1, PI3K/mTOR, aurora kinases, c-MET, polo-like kinases, and JAK/STAT as synthetic lethalities in Snail+ prostate cancer." (PMID 37228586, 2023).
prostate carcinoma (continued). "In this study, we investigated differences in expression of XPO1 and PDCD6IP on well‐characterized prostate cancer cohorts using mass spectrometry and tissue microarray (TMA) immunohistochemistry to determine their diagnostic and prognostic value." (PMID 31018022, 2019). "By targeting XPO1/ARv signaling, SINE suppressed prostate cancer (PCa) growth in vitro and in vivo and potentiated the anti-cancer activity of anti-AR agents, enzalutamide and abiraterone." (PMID 30450161, 2018). "Identification of exosomal proteins using high performance LC-FTMS resulted in the discovery of PDCD6IP, FASN, XPO1 and ENO1 as new candidate biomarkers for prostate cancer." (PMID 24391718, 2013). "Additionally, double gene molecular subtype analysis with SUMO1, SUMO2, and XPO1 genes revealed survival outcome differences across molecular subtypes, further emphasizing NOP58’s critical role in prostate cancer biology and patient prognosis (Figures A1–C5)." (PMID 39494345, 2024). "These screens identified multiple therapeutic vulnerabilities of Snail+ prostate cancer cells, including several with known functions in prostate cancer and/or EMT, such as aurora kinases, MET, polo-like kinases, and CRM1/XPO1." (PMID 37228586, 2023). "The dual-gene molecular subtype analysis with SUMO1, SUMO2, and XPO1 genes revealed significant differences in survival outcomes across molecular subtypes, further emphasizing the potential impact of NOP58 on SUMOylation, a key post-translational modification, in prostate cancer." (PMID 39494345, 2024).